IL13 (interleukin 13)
Diseases named in the same sentence as IL13 in open-access papers (continued):
Sharing a sentence is not in itself a finding about the gene and the disease.
asthma (continued). "Asthma-associated serum cytokines (IL-13 and IL-17A) were modulated by oral ginger." (PMID 39770492, 2024). "Interleukin (IL) genes, particularly IL-4 and IL-13, have been linked to asthma pathogenesis." (PMID 38699097, 2024). "IL-4, together with IL-5 and IL-13, are Type 2 (T2)-high asthma-associated cytokines that are assumed to provide the main asthma manifestations, such as bronchial hyperreactivity, mucus hyperproduction, immunoglobulin E (IgE) synthesis, and airway eosinophilia." (PMID 39767651, 2024). "Genetic association studies have uncovered those variations within the IL33 gene, the ST2 (IL1RL1) receptor, the ROR-α (RORA) transcription factor, and IL13—all pivotal in the development and activation of ILC2s—are linked to asthma with a high presence of type 2 helper T cells." (PMID 38680486, 2024). "The discovery of the mechanism underlying allergic disease, mouse models of asthma, and bronchoscopy studies provided initial insights into the role of Th2-type cytokines, including interlukin (IL)-4, IL-5 and IL-13, which became the target of monoclonal antibody therapy." (PMID 37259416, 2023). "Furthermore, circARRDC3 was found to enhance inflammation and mucus production in nasal epithelial cells stimulated with IL-13 in allergic rhinitis, a substantial risk factor for the development of asthma." (PMID 38078005, 2023). "The role of eosinophilic airway inflammation, a classic feature of asthma predominantly driven by IL-5 and IL-13, in bronchiectasis is unclear, but association with disruption of the airway epithelium through eosinophil degranulation and increased mucus production is plausible." (PMID 37780108, 2023). "Notably, AEC and NEC-derived correlated gene signatures including CCL26, CLCA1 and POSTN were involved in IL-13 signaling, where IL-13 signaling of the airway epithelium is associated pathophysiology of asthma and airway inflammation." (PMID 37438356, 2023). "In addition, asthma-associated SNPs in IL-4R, IL-13, and STAT6 gene loci are inversely correlated with the occurrence of GBM." (PMID 37429945, 2023). "Both Th1 and Th2 cytokines, including IFN-γ, IL-4, and IL-13 have been shown to induce asthma; however, the underlying mechanisms remain unclear." (PMID 36824812, 2023). "Furthermore, we have identified TGF-β1 and IL-13 as contractile modulators from among the larger set of asthma associated cytokines." (PMID 37206658, 2023). "A recent review has compiled data describing that individuals with asthma may be predisposed to features of airway remodeling based on single nucleotide polymorphisms in remodeling-associated genes, including IL13, PLAUR, VEGFA, and CHI3L1." (PMID 37773065, 2023). "CRSwNP and asthma share similar pathophysiology and are associated with eosinophilic infiltration and Th2 cytokines such as interleukin-4, interleukin-5, and interleukin-13 (IL-4, IL-5, and IL-13) as well as high levels of local immunoglobulin-E (IgE)." (PMID 37674852, 2023). "By compromising the integrity of the sinonasal and bronchial epithelial layers in patients with asthma and nasal polyposis, IL-4 and IL-13 cause a dysfunction of the airway epithelial barriers, thus increasing their permeability to aeroallergens and infectious agents." (PMID 37240477, 2023). "Notably, we found that human TH2 cells also differentially express αvβ3, and that this expression is correlated with the co-expression of the asthma-associated cytokine IL-13." (PMID 36550322, 2023). "A variety of inflammatory cells and cytokines participate in asthma, which inflammatory cytokines (such as IL-13) could cause ferroptosis of airway epithelial cells and which ones do not, a further study is required." (PMID 36862916, 2023). "Periostin is an extracellular matrix protein produced by airway epithelial cells and fibroblasts upon activation by IL-4 or IL-13, which is implicated in tissue remodeling and correlated with lung function decline as well as asthma exacerbations (despite high-dose ICS therapy)." (PMID 37035303, 2023).
asthma (continued). "For this reason, periostin quantification could help in the identification of patients with severe uncontrolled asthma and those susceptible to anti-IL-13 therapy." (PMID 37762787, 2023). "Multiple cytokines, including IFNγ, IL-4, and IL-13 are associated with asthma; however, the mechanisms underlying the effects of these cytokines remain unclear." (PMID 38081868, 2023). "Classically, this form of asthma is associated with an increase in serum immunoglobulin E (IgE) antibodies and eosinophilia, as well as the presence of interleukin 4 (IL-4)–, IL-5-, and IL-13-producing cells in bronchoalveolar lavage (BAL)." (PMID 36089628, 2023). "Toxocara infection modulates the immune response to Th2 and the secretion of IL4, IL5, and IL13, which could theoretically be associated with asthma." (PMID 36250067, 2022). "Interestingly, 21% of genes within 1500 kb of an assayed CpG site were in or near a minimum of one IL‐13‐responsive CpG site, and were significantly enriched for genes associated with asthma." (PMID 35344303, 2022). "When the Th2 expression is hyperactive, the IL-4 and IL-13 synthesize specific allergen IgE, which binds to the eosinophil/mast cell membrane high-affinity substance and induces the release of inflammatory waterfall that causes asthma." (PMID 35859797, 2022). "Therefore, we conclude that in our case, DEPs induced T-helper-2-type-associated asthma involving eosinophils, IL-4, and IL-13." (PMID 36293642, 2022). "Asthma and AD are frequently associated with atopy and are characterized by elevated levels of type 2 cytokines (IL-4, IL-5, IL-13), which cause IgE production, mast cell activation, and basophil and eosinophil recruitment, well-known cellular actors in IgE-mediated inflammatory response." (PMID 36364420, 2022). "Therefore, both IL-4 and IL-13 significantly participate in the induction of bronchial epithelial dysfunction, which is a hallmark of asthma." (PMID 35350765, 2022). "IL-4 and IL-13 are called prototypical type 2 cytokines, which can cause immunoglobulin E (IgE) production and eosinophils can transport to the airways, thus triggering an asthma attacks." (PMID 36530558, 2022). "In fact, the level of Th1 cytokines IL-12 and IFN-ɣ as well level of Treg cytokine IL-10 in lung of asthma mice was lower than control, and inversely, Th2 cells response-associated the cytokines IL-4, IL-5, and IL-13 had a significant increase in lung of asthma mice compared to the control group." (PMID 36685604, 2022). "Although the assessed inflammation parameters showed significant differences in IL-4 and IL-13, their association with allergic disorders such as asthma suggests that these changes could be driven by factors external to the dietary intervention." (PMID 36235579, 2022). "Although the exact role of sex in this physical defense mechanism remains unclear, it is possible that the female-predominant IL-13 production observed in patients with asthma may be associated with the defective functional activity of tight junction proteins." (PMID 35625578, 2022). "It is broadly known that IL-13 is a cytokine involved in the Th2 immune response and its elevation is closely associated with several respiratory diseases, such as asthma, COPD, polyposis, and allergy, notably involved in hypersecretion of mucus in such diseases." (PMID 35686128, 2022). "Excessive levels of IL-13, and the functionally related IL-4, are associated with increased allergic responses (Th2 inflammation and asthma) and resistance to parasites; the inclusion of inhibitory receptors of these Th2 molecules in vaccines has augmented immunity to infections such as HIV." (PMID 36060742, 2022). "Interestingly, it is known that Surfactant D deficient mice have excessive IL-13 secretion and IL-13 plays a role in the development of asthma." (PMID 35372166, 2022). "Similarly, the lead variant at the IL5/IL13 locus linked with a decreased risk of asthma was associated with an increased risk of psoriasis." (PMID 34103634, 2021).
asthma (continued). "A hallmark of asthma is elevation in the levels of Th2-type cytokines, such as IL-4 and IL-13." (PMID 34580637, 2021). "Numerous reports have shown that IL‐13 causes exacerbation of asthma." (PMID 33534941, 2021). "Additionally, IL-13 serum levels serve as a biomarker of eosinophilic airway inflammation and are associated with asthma severity, but their levels in biological samples are very low and difficult to use clinically." (PMID 34439751, 2021). "Particularly, type 2 (T2)-high asthma is a complex endotype associated with high type 2 inflammatory markers including immunoglobulin E (IgE), interleukins (IL)-4, IL-5, and IL-13, and it is characterized by AHR, eosinophilia, and excessive airway mucus production." (PMID 34572466, 2021). "This suggests that residual cytokine activity in mice vaccinated with kinoids might sustain IgG production, while reducing the pathogenic functions of IL-4 and IL-13 in asthma." (PMID 33976140, 2021). "However, the prolonged presence of these cytokines in the lungs, especially IL-13, have been associated with asthma exacerbation." (PMID 35387053, 2021). "To test that hypothesis, we analyzed the response to HRV16 infection in the bronchial epithelium differentiated in vitro and stimulated with cytokines to reproduce the structural changes associated with asthma, such as IL-13-induced MCM and TGF-β-induced EMT." (PMID 34140575, 2021). "IL-4, IL-5, and IL-13 are type 2 cytokines associated with asthma." (PMID 35111694, 2021). "In the context of interleukin-13 (IL-13)-induced lung inflammation, a cytokine widely implicated in a variety of asthma phenotypes, the downstream activation of ERK leads to eosinophilic inflammation, mucus production, airway hyperresponsiveness and remodeling." (PMID 34862427, 2021). "Both IL-4 and IL-13 cause immunoglobulin class switch to IgE during asthma." (PMID 35386975, 2021). "Foxp3 and IL-13 gene acetylation is associated with childhood asthma." (PMID 34566492, 2021). "These cytokines are important in asthma: IL-13 and IL-4 promote antibody class switching to IgE in B cells, IL-13 can also act on smooth airway muscle cells, causing bronchoconstriction and aiding in the remodeling of airways, and IL-5 stimulates the production of eosinophil." (PMID 34831860, 2021). "IL-13 induces mucus metaplasia, which causes airway obstruction in asthma." (PMID 34822557, 2021). "Regarding the IL13 rs1800925 polymorphism, children who carried CC genotype and were exposed to visible mold had a significantly increased risk of childhood asthma with an adjusted OR of 1.79 (95% CI 1.28–2.52), compared to children who carried CC genotype without the exposure." (PMID 33810791, 2021). "If this function of IL-13 is confirmed in humans, the long-term application of neutralizing IL-13 therapies might cause more damage to the airways than it helps to control asthma." (PMID 31979396, 2020). "Notably, the reQTL for IL13 in PHA-stimulated T cells colocalised with GWAS hits associated with asthma, allergic sensitisation, and allergic disease." (PMID 32724101, 2020). "Importantly, both of these cytokines have been implicated in asthma, each defining important asthma endotypes: IL-13 is associated with the type 2 (T2)-high endotype, IL-17 with the Th17-high endotype, and IL-13+IL-17 with the mixed T2/Th17 endotype." (PMID 32690065, 2020). "In addition, the miR-34/449 family (miR-34b, miR-34c, miR-449a, and miR-449b) were shown to be suppressed in bronchial brushings from individuals with asthma, which was associated with an increased IL-13 expression." (PMID 33255348, 2020). "miR146a-inhibitor attenuated OVA-induced allergic asthma by increasing Th1 cytokines in OVA-induced allergic asthma model, and the treatment of miR146a-inhibitor can reduce the inflammation caused by asthma, followed by the down-regulation of IL-5 and IL-13 in sorted ILC2." (PMID 32600285, 2020).
asthma (continued). "However, IL13, locating in the same chromosomal region, showed more evidence on association with asthma." (PMID 33133517, 2020). "Furthermore, the increase in TGF-β expression in the mouse lung post-IR depends on IL-13, a type 2 cytokine, which is also tightly associated with asthma." (PMID 32117962, 2020). "Moreover, environmental pollutants have been associated with some asthma phenotypes through the mediation of IL-13 and DNA methylation." (PMID 32610702, 2020). "IL-13 may be the driver of goblet cell hyperplasia and smooth muscle contractility in type 2-associated asthma." (PMID 31395084, 2019). "Similarly, Cldn18 expression levels were significantly reduced in brush samples of human epithelial cells from patients with Th2-high asthma endotype that was linked to IL-13 signaling." (PMID 31262043, 2019). "Household ETS and interleukin-13 gene (IL-13) variants may have interactive effects on childhood asthma phenotypes." (PMID 31921716, 2019). "However, when adjusting our regression analysis for asthma the positive association of maternal AD on IL-13 was sustained." (PMID 31428082, 2019). "Asthmatics experimentally infected with rhinovirus had increased viral titres compared to infected healthy controls, with greater airway inflammation, bronchial hyperreactivity, and reductions in lung function associated with increased levels of IL-4, IL-5 and IL-13 in BAL." (PMID 30764493, 2019). "Furthermore, CD38KO mice fail to develop an asthmatic airway phenotype following sensitization and challenge with allergen as well as following intranasal challenge with IL-13, a Th2 cytokine implicated in the pathogenesis of asthma." (PMID 29576747, 2018). "In animal models, deficiency of multiple genes from the IL-13 network can impact on asthma-related traits, including allergic sensitization and/or inflammation (ALOX1551, CYBB52), and airways hyperresponsiveness and mucus production/goblet cell hyperplasia (POSTN53, SERPINB3/454)." (PMID 29367592, 2018). "Group II ILCs specifically, secrete the cytokines IL-5, IL-13, IL-9, amphiregulin, and low quantities of IL-4 and have been linked to several lung-associated conditions including pathogen infections (viruses and helminths), asthma, and pulmonary fibrosis." (PMID 30413212, 2018). "As IL‐18 stimulates T cells to produce increased IFN‐γ, IL‐13 and IL‐5 23, and IL‐13 and IL‐5 are potent Th2 cytokines, which play key pro‐inflammatory role in atopic asthma, it is believed that IL‐18 ought to be a causative factor for asthma." (PMID 28922563, 2018). "The importance of IL-13 in regulating the pathogenesis of asthma in humans was demonstrated by genome-wide association studies, showing an association between polymorphisms of IL-13 and its receptor and asthma susceptibility." (PMID 28704401, 2017). "Our results suggested that IL-13 +1923C/T polymorphism contributed to the development of asthma." (PMID 28057889, 2017). "Dupilumab, a blocker of both IL-4 and IL-13, may be of utility in asthma and EoE-associated remodeling." (PMID 28831387, 2017). "Genetic polymorphisms in IL-13 gene might influence its function, thus involved in the pathogenicity of asthma." (PMID 28057889, 2017). "The most important characteristic feature of asthma is chronic airway inflammation which is associated with increased number of Th2lymphocytes and their cytokines (IL-4, IL-5, IL-9, and IL-13) while Th1 lymphocytes and their cytokines (IL-2, IFN-γ, and IL-12) are reduced." (PMID 28824424, 2017). "Notably, substitutions in the central immune regulator IL13 correspond to a polymorphism linked to asthma susceptibility in humans." (PMID 28854632, 2017). "Therefore, we conducted this meta-analysis to reassess the association of IL-13 +1923C/T polymorphism with asthma risk based on all the available case-control studies." (PMID 28057889, 2017).
asthma (continued). "Eight articles reported the association between IL-13 +1923C/T polymorphism and IgE levels in serum; however, the relevant data could only be extracted from five of them, including 569 asthma patients and 399 controls." (PMID 28057889, 2017). "Furthermore, the CHIA enzyme has been found to be a downstream protein of interleukin-13, a cytokine implicated in the effect of human asthma." (PMID 29233108, 2017). "In our study, IL-4 and IL-13 were positively associated with Easy-to-Control asthma." (PMID 28686637, 2017). "The novelty of the current study is that high serum periostin concentrations appears to predict acute asthma exacerbations in the following year, providing evidence for the potential association between persistent TH2- or IL-13–driven inflammation and greater risk for loss of asthma control." (PMID 27965769, 2016). "Therefore, excessive cytokines IL-4, IL-5, and IL-13 produced by Th2 cells are significant risk factors in asthma pathogenesis." (PMID 27870920, 2016). "Previous study showed that Belamcandae and Ephedrine Decoction can improve the immune function of the patients (effectively preventing hypersensitivity), improve clinical effects in the treatment of pediatric cough-variant asthma, and modify IL-10 and IL-13 serum levels." (PMID 27378824, 2016). "After adjusting for multiple testing and potential confounders, SNP rs848 in the IL13 gene region is significantly associated with a continuous measure of symptom severity in adult subjects with ever asthma, who were identified from the general population in Italy." (PMID 26986948, 2016). "We then searched for clinical conditions that could benefit from the same experimental approach using genes associated with the M(IL-4, IL-13) phenotype, such as asthma and pulmonary fibrosis, and constructed another list of genes with the GSEA tool." (PMID 26302899, 2015). "Polymorphisms in IL13 and IL13Rα1 have been associated with asthma and elevated IgE." (PMID 26540410, 2015). "IL-13 polymorphisms were consistently associated with asthma and serum IgE in asthma populations." (PMID 26064160, 2015). "Additionally, our study supports the findings that interleukin-13 has been implicated as a key cytokine in smooth muscle hyperreactivity on asthma, since we demonstrated an increased contractility in response to Cch in airway smooth muscle induced by IL-13." (PMID 25890178, 2015). "IL-13 has been reported to play an indispensable role in mounting bronchial hyperreactivity (BHR) and goblet cell hyperplasia, caused by elevated expression of the mucin proteins MUC5AC and MUC5B, leading ultimately to mucus overproduction and airway obstruction." (PMID 26346739, 2015). "Excessive production of IL-4, IL-5, and IL-13 was implicated in the development of asthma." (PMID 24936861, 2014). "Interestingly, genetic deficiency of GGT in GGTenu1 mice induced an asthma-resistant phenotype in an IL-13-driven model of allergic airway hyperreactivity." (PMID 25132819, 2014). "In the present study, however, treatment with CD86 siRNA abolished the OVA-challenge-induced elevation of IL-13 in BAL fluid, which makes it difficult to explain the differences in the effects of siRNA via variant sensitivities of IL-13-mediated asthma phenotypes to therapeutic interventions." (PMID 25344652, 2014). "In our previous study, children with the IL-13 GA+AA polymorphisms were found to be at increased risk of allergic rhinitis if they were exposed to mold in the home during their first year of life, and were associated with susceptibility of asthma." (PMID 24848505, 2014). "Association of IL-13 with asthma phenotypes, by additive genetic model." (PMID 23382814, 2013). "Therefore, we conducted a meta-analysis of all available case-control studies to evaluate the association of IL-13 +1923C/T polymorphism with asthma risk." (PMID 23841068, 2013).